RB1 (RB transcriptional corepressor 1)
Diseases named in the same sentence as RB1 in open-access papers (continued):
Sharing a sentence is not in itself a finding about the gene and the disease.
tumor (continued). "Among these genes, BRCA1, RB1, RBAK and CSMD3 are tumour suppressors, while TRRAP functions as an oncogene." (PMID 35735060, 2022). "RB1 and FBXW7 are the classical tumor suppressor genes, and their deletion or inactivation has been reported to be implicated in tumorigenesis." (PMID 36035135, 2022). "Finally, we demonstrated the ability to identify RB1 promoter DNA hypermethylation, a known cause of sporadic, non-heritable RB, as well as DNA methylation profiles that may predict an aggressive tumor subtype less likely to respond to medical therapy." (PMID 36130950, 2022). "Therefore, a plausible hypothesis is that mutations in these genes—in particular HRAS, EGFR, and RB1—were coincidental findings in individual tumours, and are not recurrent driver events in EP tumourigenesis." (PMID 34045664, 2022). "Here, we report that there are CDRs in many tumor suppressor genes, such as CDKN2A, miR31HG, PTEN, and RB1, which are commonly inactivated by SCND in various human cancers." (PMID 36531022, 2022). "Estimated common deletion regions (CDRs) were observed in many tumor suppressor genes, such as ATM, CDKN2A, FAT1, miR31HG, PTEN, and RB1, in the SNP array-based COSMIC datasets." (PMID 36531022, 2022). "It is possible that in LMS tumors with high accumulation of DNA damage, disruption of cell cycle checkpoint regulation through RB1, CDKN2A/B, MYC, FBXW7, or NF1 is necessary to maintain the viability of the tumor." (PMID 35468996, 2022). "These include the tumour suppressors, PDCD4, RB1, STK2, transcriptional regulators with reported roles in cancer, BCL9L, STAT5B and proteins that are involved in control of the cell cycle, ANAPC4, ANAPC5, RBX1." (PMID 35573784, 2022). "Six genes (DNAJB6, RB1, VIMP/SELENOS, STEAP3, BACH1, and ALOX12) had a consistent mRNA expression level in tumor samples and prognosis in the univariate Cox analysis." (PMID 34075060, 2021). "Palbociclib is a selective CDK4/6 inhibitor affecting the cell cycle progression of retinoblastoma-1 (Rb-1) wild type HCC cells and impairing tumor growth in vivo." (PMID 34572776, 2021). "Yet, the presence of RB1 is crucial for exerting therapeutic effects of CDK4/6i’s and constitutes an already proven biomarker in other tumor entities." (PMID 33161487, 2021). "Reactivation of RB1 with palbociclib halted MPNST growth both in vitro and in vivo in orthotopic (sciatic nerve) mouse tumor models." (PMID 33456709, 2021).
tumor (continued). "Like RB-1 deletion, depletion of ATP5H (a subunit of ATP synthase) confers a resistant and stem-like phenotype to tumor cells by triggering a reprogramming of mitochondrial metabolism." (PMID 34976949, 2021). "Common somatic gene mutations that regulate cellular and energy metabolism in breast cancers, such as observed in RB1 and MYC genes, demonstrate variable clonal frequencies within a tumour, possibly contributing to intra-tumour metabolic heterogeneity." (PMID 34572926, 2021). "AURKA has been identified as a synthetic lethal target for several tumor suppressors, including ARIDIA, SNF, and SMARCA4, as well as RB1." (PMID 34359608, 2021). "Further biochemical assays in cell lines confirmed that established drivers of tumor initiation and subtype implementation are indeed regulated by this ceRNET, including PTEN, RB1, STAT3, PDGFRA, RUNX1, and VEGFA." (PMID 33995499, 2021). "In-vitro studies reveal that the retinoblastoma protein (pRb) synthesized from RB1, a tumor suppressor, physiologically represses PPAR-γ expression, decreasing BAT formation." (PMID 34069148, 2021). "This includes inhibition of the retinoblastoma (RB1) and protein phosphatases 2A (PP2A) tumor suppressors and activation of oncogenic AKT and mTOR." (PMID 34199469, 2021). "In three tumours, PD37488, PD37489 and PD37496, multiple rearrangements transected RB1 as part of a wider collection of complex, intrachromosomal rearrangements." (PMID 33670346, 2021). "Glutamate metabotropic receptor 1 (GRM1) and retinoblastoma 1 (RB1) were additional alterations found in PDX15, for the patient normal, tumor, and PDX tumor tissue." (PMID 32825052, 2020). "Rb1/p107/Hells TKO and Rb1/p107 DKO mice were followed for 1 year beginning at birth for signs of tumor development." (PMID 32071286, 2020). "The Delta-24 mutation restricts viral replication to cells defective in the retinoblastoma protein tumour suppressor (RB1), allowing DNX2401 to selectively replicate in tumour cells that have lost RB1." (PMID 32645977, 2020). "RB1 is a well-known tumour suppressor protein (pRb), and DOK1 (docking protein 1) is also a tumour suppressor, which shows repressed expression in many human tumours owing to hypermethylation of its promotor region." (PMID 32616892, 2020).
tumor (continued). "To examine the ability of CANT1 to suppress tumor formation in vivo, we inoculated CANT1-overexpressing Weri-Rb1 cells and mock cells into the posterior segments of the eyes of nude mice." (PMID 32366932, 2020). "Conversely, loss of the endogenous CDK4/6 inhibitors (CDKN2A, CDKN2B, CDKN2C, and CDKN2D) or RB-family (RB1, RBL2, and RBL1) are also observed in specific tumor settings, in total the RB-pathway is subject to genetic perturbation in greater than 30% of tumors." (PMID 32242058, 2020). "For instance, the tumor suppressors PTEN and RB1 were frequently lost, while the oncogene MYC was inside a frequently amplified region, confirming the validity of the SCNA analysis to pinpoint genes relevant to tumor progression." (PMID 32858747, 2020). "RB1 and CHEK2 act as tumor suppressors, maintaining the cell in G1, whereas CCNE1 (cyclin E1) acts as an oncogene when mutated or abnormally activated." (PMID 33396315, 2020). "Interestingly, tumor and cfDNA analysis identified a different RB1 mutation, present at VAF of 1.37% in cfDNA and not detectable in the matched buffy coat, suggesting that it is likely somatic, as germline variants detected in cfDNA are typically at a VAF around 50%." (PMID 32633890, 2020). "While p16INK4a is a specific inhibitor of D-CDK4/6 kinases that promotes G1 phase arrest by RB1 activation, ARF has multiple targets through which it elicits cell cycle arrest, apoptosis, autophagy, and/or other tumor suppressive biological changes." (PMID 32344731, 2020). "EGFR and KRAS genes were classified as oncogenes and STK11, RB1 and MGA genes were classified as tumor suppressors." (PMID 32998690, 2020). "Like PTEN and Rb1, APC is a new and important tumor suppressor in neurons that normally suppresses their growth." (PMID 31024258, 2019). "In the oral model, <40% of mice develop tumors when RB1 is deleted, but the addition of HPV16 E7 to the RB1 knockout results in >90% tumor incidence." (PMID 31013597, 2019). "A small proportion of initial tumours had SNVs in the G-protein gene, GNAS (5%; 2/38), IDH1/2 (5%; 2/38), and the Rb-specific cell-cycle regulation genes CDK6 and RB1 (5%; 2/38)." (PMID 32082376, 2019). "The parallel but thus far largely unconnected impact of two critical tumor suppressor pathways, PTEN and Rb1, on post-mitotic adult sensory neurons was remarkable." (PMID 31024258, 2019).
tumor (continued). "Particularly, Rg1 and Re induce angiogenesis that contributes to wound healing and tissue regeneration, while others, such as Rb1, Rb2 and Rg3 suppress VEGF-induced angiogenesis, leading to tumor growth inhibition." (PMID 30872732, 2019). "PRMT5 regulates this pathway through direct methylation of histones H3R8 and H4R3 in the promoter region of RB1, RBL1 and RBL2 tumor suppressor genes." (PMID 30613353, 2018). "When the average tumor volume reached about 100 mm3, free PPD (20 mg/kg), Rb1 NPs, Rb1/PPD NPs (20 mg PPD-equivalent/kg) were injected into the mice, respectively." (PMID 29473838, 2018). "MiR-26a also regulates the expression of critical signaling genes such as PTEN, RB1 and MAP3K2/MEKK2, promotes tumor growth and inhibits JNK-dependent apoptosis in vivo." (PMID 30583549, 2018). "The tumor expressed decreased levels of FOXO1 and RB1 as well as increased levels of oxidative stress markers, 8-hydroxy-2′-deoxyguanosine (8-OHdG) and 4-hydroxy-2-nonenal (4-HNE)." (PMID 28887603, 2018). "Finally, we explored the idea that E7 may not be highly expressed in tumor samples harboring RB1 mutations." (PMID 29359188, 2018). "Intriguingly, some of these molecules are related to oncogenesis and tumour progression/metastasis, namely, HRAS, KRAS, TGFBR1, TGFBR2, RB1, ITGA6, ITGB4, mTOR, TSC2 and APLP2." (PMID 30258067, 2018). "When the tumor volume reached approximately 300 mm3, a single IV dose of free PPD (10 mg/kg) and Rb1/PPD NPs (10 mg respiratory syncytial virus; RSV-equivalent/kg) was administered to all mice." (PMID 29473838, 2018). "In Rb1/PPD NPs group, it should be noted that the at 24 h post-medication administration, PPD content in the tumor still remained at a relatively high level." (PMID 29473838, 2018). "The tumor suppressor genes PTEN (Phosphatase and tensin homolog), JNK (c-Jun N-terminal kinase), RB1 as well as an additional inhibitor of NF-κB, NKIRAS1 (NF-κB inhibitor-interacting Ras-like protein 1) are among the putative miR-30e* targets." (PMID 28978058, 2017). "Members of miR-200 family are usually considered as tumor suppressors and involved in EMT, and RB1 is confirmed as a direct target of miR-675." (PMID 28212565, 2017). "Tumor sections of UPEN‐RB‐175 (MYCN‐amplified, RB1+/+) stained strongly for pRb and ppRb, while the two MYCN‐amplified RB1+/− stained strongly with pRb antibody, but showed weaker staining of fewer cells with ppRb antibody." (PMID 28211617, 2017). "The calculated genomic circuit scores were, as expected, high for tumours in the Uro cluster, i.e. FGFR3+, CCND1+, RB1+, and E2F3−, both at the mRNA level and the tumour‐cell protein level." (PMID 28195647, 2017). "RB1 and BRCA2 abnormalities play a role in the development of several cancers and are considered to be tumor suppressor genes." (PMID 27741277, 2016).
tumor (continued). "Our meta-analysis was unable to find any statistical significance between HCC tumor tissues and adjacent tissues for the methylation of the remaining four genes, including MGMT, DAPK1, IGF2 and RB1." (PMID 27835605, 2016). "In the liver SCLC tumour, comparative genomic hybridization (CGH) array analysis revealed that there was a relatively large deletion in one copy of RB1 that encompassed the entire gene and the surrounding region." (PMID 25758528, 2015). "Because the RB protein is a reported positive regulator of osteogenic differentiation, we predicted that retaining one copy of the Rb1 gene in the Osx-Cre Rb1fl/+; Ptenfl/fl mice might shift the tumor formation away from adipogenic and towards osteogenic tumors." (PMID 26317218, 2015). "Therefore, RB1 might represent a predictive marker of response to therapy for various tumor types." (PMID 26160835, 2015). "Tumor growth of the complex mice treated with PBS vehicle or indicated treatments including PNS, Rg1, Rb1 or R1 were monitored and documented." (PMID 24903055, 2014). "Our IHC results for RB1 and RBL2 support the previous conclusion that large subpopulations of tumor cells are in a resting state." (PMID 25093008, 2014). "Several genes displayed correlations between epigenetic modification and clinically relevant parameters, including invasiveness (CDKN2A; DAPK; Rb1), sex (MAGE-A3), tumor size (GNAS1), and histopathological subtype (CDKN2A; MEG3; p27; RASSF1A; Rb1)." (PMID 24367530, 2013). "In GBM, there is frequent hypermethylation of tumour suppressors (RB1, EMP3, RASSF1A and BLU), cell cycle regulators (p16INK4a and p15INK4b), DNA repair genes (MGMT, MLH1), and genes involved in tumour invasion and apoptosis (DAPK, TIMP3 and CDH1)." (PMID 22771539, 2013). "Whole genome shotgun sequencing detected the rearrangements involving several known tumor suppressors in 20 tumor/normal sample pairs, which were further confirmed by RNA sequencing including PTEN, RB1, NOTCH1, NF1, and CDKN2A." (PMID 23109866, 2012). "Together, this work reveals a novel role for rb1 in the establishment of RGC axon projections during development and establishes a unique model for understanding the developmental and tumor suppressor roles of the rb1 gene." (PMID 23209449, 2012). "Strikingly, the observed rate of homozygous deletions within LRP1B in human cancer cell lines is equivalent to or higher than known recessive tumor-suppressor genes such as PTEN, RB1 and SMAD4 in the same cell line dataset." (PMID 20942901, 2010). "RB1 deletion was infrequent with much lower frequency in dysplastic lesions than invasive samples, suggests it less likely to be a candidate TSG in this tumor." (PMID 20226061, 2010).